AXIN2 (axin 2)
Diseases named in the same sentence as AXIN2 in open-access papers (continued):
Sharing a sentence is not in itself a finding about the gene and the disease.
gastrointestinal polyp (3 papers, 2012 to 2023). A polypoid tumor that arises from any part of the gastrointestinal tract and protrudes into the lumen. "The clinical phenotype is variable and in addition to gastrointestinal polyps, individuals with AXIN2 mutations tend to have hypo- and oligodontia." (PMID 37626374, 2023). "Although rare, loss-of-function germline mutations in the gene AXIN2 (OMIM 604025), encoding for a scaffolding component in the β-catenin destruction complex, also predispose to gastrointestinal polyps and cancer." (PMID 37626374, 2023). "Germline mutations in AXIN2 are associated with absence of permanent teeth (hypo- and oligodontia) and predisposition to gastrointestinal polyps and cancer." (PMID 37626374, 2023).
glioblastoma (3 papers, 2016 to 2020). The most malignant astrocytic tumor (WHO grade IV). "In accordance, human glioblastoma display a weak but significant negative correlation between USP15 and AXIN2 expression." (PMID 29299163, 2017).
Hypertension (3 papers, 2014 to 2022). The presence of chronic increased pressure in the systemic arterial system. "Although β-catenin was also expressed in endothelial cells of aorta, Axin2 expression was not induced in endothelial cells 1 week after AngII infusion, suggesting that β-catenin signalling was more potently activated in aortic VSMCs rather than endothelial cells at the early stage of hypertension." (PMID 25716000, 2015).
intestinal tumors (3 papers, 2021 to 2025). "Quantitative RT-PCR analysis of the isolated tumors showed that expression of the WNT target genes and stem cell markers Lgr5, Ascl2, and Axin2 were suppressed in the Usp7 cKO tumors, suggesting that Usp7 depletion inhibits WNT signaling in the Apc-deficient intestinal tumors." (PMID 36669491, 2023).
lymphoma (3 papers, 2012 to 2021). A malignant (clonal) proliferation of B- lymphocytes or T- lymphocytes which involves the lymph nodes, bone marrow and/or extranodal sites. "GNG7, AXIN2, HIF1A, FGF2 and PPAP2B are found upregulated in our study in the same way as it is found in association with lymphoma disease according to literature." (PMID 30679748, 2019). "Moreover, the high Axin2 expression in the majority (73%) of lymphomas in combination with the universally up-regulated Lef1 expression indicates a marked increase in Wnt signaling in these lymphomas." (PMID 23185135, 2012). "We have recently shown that PRMT5 promotes WNT/β‐CATENIN proliferative signalling through transcriptional repression of pathway antagonists, AXIN2 and WIF1, in three different types of lymphoma cells." (PMID 33462997, 2021). "In contrast to our results in the different lymphoma cell types, we found that AXIN1, AXIN2 and WIF1 mRNA levels were elevated in transformed breast epithelial cells." (PMID 33462997, 2021).
neuroblastoma (3 papers, 2016 to 2018). Neuroblastoma (NB) is the most common solid, extracranial childhood tumor. "Real-time quantitative PCR demonstrated that Prickle1 expression was inversely correlated to active β-catenin/Axin2 levels in neuroblastoma cells." (PMID 27036398, 2016). "All nine investigated neuroblastoma cell lines displayed active β-catenin, i.e. the dephosphorylated nuclear form, as well as the canonical Wnt target gene Axin2, regardless of MYCN gene amplification status." (PMID 27036398, 2016).
non-small cell lung carcinoma (3 papers, 2021 to 2023). A group of at least three distinct histological types of lung cancer, including non-small cell squamous cell carcinoma, adenocarcinoma, and large cell carcinoma. "In non-small cell lung cancer (NSCLC), overexpressed miR-582-3p maintains stemness features by negatively targeting the regulators of Wnt signalling Axin2, DKK3 and SRP1 for degradation, thereby increasing β-catenin mediated Wnt activity." (PMID 35101137, 2022).
pancreatic ductal adenocarcinoma (3 papers, 2021 to 2022). An infiltrating adenocarcinoma that arises from the epithelial cells of the pancreas. "LINC01133 has been shown to be secreted into EVs from pancreatic ductal adenocarcinoma cells and is transferred to cancer cells to silence AXIN2/GSK3 and activate the Wnt/β-catenin pathway, which promotes EMT." (PMID 35747817, 2022).
synovial sarcoma (3 papers, 2016 to 2020). "Several other genes pertaining to these networks may be dysregulated in synovial sarcoma, including LEF1, AXIN2, TCF7, and FZD homologues in the Wnt/β-catenin, HES1, and NOTCH1 in the Notch, as well as SMO and PTCH in the Sonic Hedgehog pathways." (PMID 32322158, 2020).
ameloblastoma (2 papers, 2021). The most common odontogenic tumor, arising from the epithelial component of the embryonic tooth and usually affecting the molar-ramus region of the mandible or maxilla. "In human ameloblastoma, there was also strong immunostaining of AXIN2 in comparison to a normal oral mucosa, and high expression levels of AXIN2 in human SCC were associated with tumor size and recurrence." (PMID 34072517, 2021).
cervical cancer (2 papers, 2021 to 2024). A primary or metastatic malignant neoplasm involving the cervix. "The Wnt-driven GREM1 as a carcinogenic gene promoting proliferation in cervical cancer and the Wnt target gene AXIN2 were upregulated in xenograft tumors from LGR6high HeLa, SiHa, and CaSki cells." (PMID 34489551, 2021).
cholangiocarcinoma (2 papers, 2025). A carcinoma that arises from the intrahepatic biliary tree (intrahepatic cholangiocarcinoma) or from the junction, or adjacent to the junction, of the right and left hepatic ducts (hilar cholangiocarcinoma). "Furthermore, correlation analysis using cholangiocarcinoma datasets from The Cancer Genome Atlas (TCGA-CHOL) showed that WNT pathway genes (AXIN2, CTNNB1, LEF1) positively correlated with TIC signature genes (KIT, SALL4, CD44, SOX2)." (PMID 39774471, 2025).
gastric adenoma (2 papers, 2020 to 2023). A neoplastic polyp that arises from the stomach. "This is the first case reported on a patient with a pathogenic, germline AXIN2 variant and an olfactory neuroblastoma or a gastric adenoma." (PMID 32807118, 2020). "This is the first AXIN2 germline pathogenic variant case reported with an olfactory neuroblastoma and also the first case with a gastric adenoma." (PMID 32807118, 2020). "In light of the recently reported co-occurrence of germline AXIN2 mutation with a gastric adenoma, one-off gastroscopy in carriers might gain insight whether gastric adenomas are part of the AXIN2-related phenotype spectrum." (PMID 37626374, 2023). "Furthermore, a single case study more recently suggested that the AXIN2-related phenotype spectrum might be expanded by neuroblastomas and gastric adenomas." (PMID 37626374, 2023).
injury (2 papers, 2022 to 2024). Damage inflicted on the body as the direct or indirect result of an external force, with or without disruption of structural continuity. "For example, WNT-responsive AEC2s (expressing axis inhibition protein 2 or AXIN2), termed alveolar epithelial progenitors (AEPs), have been shown to represent a stable lineage during homeostasis, and are capable of rapid expansion following acute lung injury." (PMID 38891054, 2024).
lymph node metastasis (2 papers, 2020 to 2022). "Moreover, Axin2 and Snail expression were significantly associated with some of the classic poor prognostic indicators, such as lymph node metastasis, vascular invasion, and bone invasion in various types of cancers including OSCC." (PMID 35875099, 2022). "Both high Axin2 expression and high Snail expression showed a significant association with T stage (p < 0.001 and p = 0.031), lymph node metastasis (both p < 0.001), vascular invasion (p = 0.01 and p = 0.019), and bone invasion (p < 0.001 and p = 0.028) in the present study." (PMID 33046030, 2020). "In multivariate analysis, lymph node metastasis, desmoplasia, Axin2 expression, and Snail expression were independent poor prognostic factors in our cohort." (PMID 33046030, 2020).
Obesity (2 papers, 2021 to 2023). Accumulation of substantial excess body fat. "Obesity-associated inflammation is linked to the up-regulation of active β-Catenin, a pivotal component in the Wnt pathway, and several Wnt signaling target genes (Cyclin D1 and Axin 2)." (PMID 37185433, 2023).
pancreatitis (2 papers, 2016). Inflammation of the pancreas. "Previous studies have demonstrated a role for activated Wnt signaling in pancreatitis-induced tissue regeneration, which is consistent with the present study where AXIN2 expression was induced in response to pancreatitis." (PMID 27764193, 2016). "Consistent with previous data wild-type mice with pancreatitis led to a significant increase in AXIN2 expression, a biomarker for Wnt signaling." (PMID 27764193, 2016). "We evaluated activation of the Wnt signaling pathway by using a Wnt reporter mouse strain expressing β-galactosidase under the control of the Axin2 promotor during pancreatitis induced formation of precancerous lesions." (PMID 27555909, 2016). "AGR2-/-null mice, however, showed higher baseline AXIN2 expression, which was not induced with pancreatitis." (PMID 27764193, 2016). "The AGR2-/-null mouse exhibited constitutive expression of AXIN2, suggesting that Wnt signaling is active, but was not induced with pancreatitis." (PMID 27764193, 2016). "In Axin2+/lacZ mice without pancreatitis no β-galactosidase stained tubular complexes were observed, whereas a strong β-galactosidase staining was observed in tubular complexes during chronic pancreatitis." (PMID 27555909, 2016).
prostate tumor (2 papers, 2008 to 2021). "Quantitative RT-PCR analysis revealed that Axin2 was expressed at higher levels in PC3, DU145 and LNCaP cell lines and human prostate tumor xenograft samples (LuCaP35 and LuCaP77), than normal or non-tumorigenic human prostate epithelial cells such as PrEC and BPH1 cells." (PMID 18478098, 2008).
psoriasis (2 papers, 2012 to 2023). An autoimmune condition characterized by red, well-delineated plaques with silvery scales that are usually on the extensor surfaces and scalp. "The study pointed out that the expression of gene Axin2 in normal tissue was significantly higher than that of psoriasis tissue." (PMID 37373186, 2023). "Likewise, the downregulation of the canonical wnt inhibitor DKK2, CTNNBIP1 (ICAT), Axin2, as well as FRZB (SFRP3) is common to SCC and psoriasis." (PMID 22384081, 2012). "Interestingly, the specific activation of β-catenin in the granular layer, as well as Axin2, shown here may explain the slight downregulation of canonical Wnt signalling noted in psoriasis, since this layer fails to be formed in that disease." (PMID 22384081, 2012).
Sagittal craniosynostosis (2 papers, 2020 to 2021). A kind of craniosynostosis affecting the sagittal suture. "We assume that this Axin2 mutation predisposes to sagittal craniosynostosis but extra environmental insults are needed to initiate the disease." (PMID 34134783, 2021). "Consistently with our results, a de novo loss-of-function mutation in AXIN2 gene has been recently reported in a patient diagnosed with sagittal craniosynostosis." (PMID 32575385, 2020). "In addition, Axin2 missense mutation (c.1181G > A: p.R394H, rs200899695) is likely to be deleterious by in silico predication; however, only the proband received additional risk factors (persistent breech presentation and intrauterine growth restriction) developed sagittal craniosynostosis." (PMID 34134783, 2021).
thymoma (2 papers, 2015 to 2024). A neoplasm arising from the epithelial cells of the thymus. "Indeed, Axin2, Cyclin D1 and c-Myc were upregulated in the manifest thymomas compared to the CD45− thymic stromal cells isolated from non-Tg thymi." (PMID 26101855, 2015).
triple-negative breast carcinoma (2 papers, 2013 to 2019). An invasive breast carcinoma which is negative for expression of estrogen receptor (ER), progesterone receptor (PR), and human epidermal growth factor receptor 2 (HER2). "Our data, which revealed a upregulation of AXIN2, DKK1 and MYC in the TamR cells, are largely consistent with findings documented in current literature on triple negative breast cancer." (PMID 23547709, 2013). "Intriguingly, Sox9 inhibition (whether transient or stable) resulted in significantly reduced expression of AXIN2, a classical Wnt/β-catenin target gene and of the Wnt receptor and target gene FZD4, in tamoxifen-resistant cells and in triple-negative breast cancer cells." (PMID 30622340, 2019).
acute pancreatitis (1 paper, 2016). An acute inflammatory process that leads to necrosis of the pancreatic parenchyma. "No β-galactosidase staining was observed in the pancreas of hyperglycemic Axin2+/+ mice after acute pancreatitis." (PMID 27555909, 2016).
adenosarcoma (1 paper, 2017). A low grade malignant neoplasm characterized by the presence of a benign epithelial component (tubular and cleft-like glands) and a low grade sarcomatous component that contains varying amounts of fibrous and smooth muscle tissues. "In addition, the Wnt signaling pathway was significantly altered in adenosarcomas, which harbored, among other alterations in Wnt pathway‐related genes, homozygous deletions of APC (1/19, 5%) and SMARCA4 (1/19, 5%) and nonsynonymous mutations affecting AXIN1 (1/19, 5%) and AXIN2 (1/19, 5%)." (PMID 28267263, 2017).
adrenocortical carcinoma (1 paper, 2023). "In adrenocortical carcinoma, aberrant β-catenin status correlates with upregulation of its target genes LEF1, AXIN2, and ISM1, which are not increased in ACA, indicating that transcriptionally active β-catenin influences proliferative phenotype and the transcriptional level of TCF/LEF target genes." (PMID 38269250, 2023).
Alzheimer disease (1 paper, 2024). A progressive, neurodegenerative disease characterized by loss of function and death of nerve cells in several areas of the brain leading to loss of cognitive function such as memory and language. "These categories include WNT (WNT1, WNT3A, WNT6, AXIN2, TNF2, MMP7), Alzheimer disease presenilin (WNT1, WNT3A, WNT6, MMP7), cadherin (WNT1, WNT3A, WNT6) and Notch (LFNG, HES1) signaling pathways." (PMID 38928376, 2024).
anodontia (1 paper, 2016). Anodontia is an extreme developmental dental anomaly characterized by the complete absence of all teeth. "We scanned another female with non-syndromic anodontia and her younger brother with the same gene mutations of the PAX9,MSX1,AXIN2 and EDA, but without developmental abnormalities in the dentition." (PMID 26759063, 2016).
aortic stenosis (1 paper, 2022). Aortic valve stenosis is a aortic valve disease caused by the incomplete opening of the aortic valve. "Noteworthy, among these genes, immunoglobulin κ constant (IGKC) and IGKV1-12 are involved in antigenic responses, AXIN2 plays a well-known role in vascular calcification, and COL12A1 has been implicated in aortic stenosis and osteo-chondrogenic differentiation." (PMID 36437309, 2022).
Barrett esophagus (1 paper, 2019). Esophageal lesion lined with columnar metaplastic epithelium which is flat or villiform. "Moreover, CyclinD1 and Axin2 were higher expressed in Barrett’s esophagus than in normal squamous epithelium from human specimen biopsies." (PMID 30841855, 2019).
brain tumor (1 paper, 2023). "To compare the data quality of RRST and standard Visium datasets obtained from the pediatric brain tumor samples, we examined the expression of WNT-signaling genes, including AXIN2, DKK4, LEF1 and CTNNB1 and two known targets of the WNT pathway SP5, GAD122,23." (PMID 36720873, 2023).
chronic lymphocytic leukaemia (1 paper, 2022). "Here, the authors show that a germline variant induces transcription factor nucleation through chromatin compaction leading to AXIN2 up-regulation and is associated to better prognosis in chronic lymphocytic leukaemia." (PMID 35440565, 2022).
chronic pancreatitis (1 paper, 2016). A chronic inflammatory process causing damage and fibrosis of the pancreatic parenchyma. "No β-galactosidase staining was observed in the pancreas of hyperglycemic Axin2+/+ mice during chronic pancreatitis indicating that β-galactosidase staining is dependent on the knock in allele of β-galactosidase into the Axin2 locus." (PMID 27555909, 2016).
co-infection (1 paper, 2025). "Consistently, the results showed that NGOs displayed a significant upregulation of TFF1, VIL1, and Lgr5 at 24 h after co-infection of H. pylori with EBV and a downregulation of CD44 and Axin 2 compared to the H. pylori or EBV-alone groups." (PMID 40833108, 2025).
colorectal adenoma (1 paper, 2014). An adenoma that arises from the colon or rectum. "Using real-time PCR, we found that the expression of downstream transcriptional targets of the β-catenin/TCF signaling pathway that are known to be elevated in colorectal adenoma and carcinomas, such as AXIN2, NKD1, and IRS1, were not decreased by RAP treatment in the HCECs." (PMID 24763434, 2014).
combined immunodeficiency (1 paper, 2022). A broad classification of inherited disorders presenting at birth that affect both the cell-mediated and humoral aspects of the immune response. "For example, A missense mutation in TFRC, encoding transferrin receptor 1, causes combined immunodeficiency and TFRC also promotes epithelial ovarian cancer cell proliferation and metastasis via up-regulation of AXIN2 expression." (PMID 35818395, 2022).
congenital heart defects (1 paper, 2020). "This study aimed to investigate possible associations of the susceptibility to congenital heart defects (CHDs) with AXIN1 rs1805105, rs12921862 and rs370681 gene variants and haplotypes, and AXIN2 rs2240308 gene variant." (PMID 33096676, 2020). "The present study is an exploratory research that reveals significant positive associations between susceptibility to congenital heart defects and AXIN1 rs1805105, rs12921862 and rs370681 (C-C-C and C-C-T) haplotypes and AXIN2 rs2240308 variant." (PMID 33096676, 2020).
congenital septal heart defects (1 paper, 2020). "According to our knowledge, only two published studies investigated one or two of the mentioned variants in patients with congenital septal heart defects and none of them investigated the AXIN2 rs2240308 variant in relation to CHD." (PMID 33096676, 2020).
diabetic nephropathy (1 paper, 2011). "We assessed tag and potentially functional single nucleotide polymorphisms (SNPs; n = 31) in four key Wnt pathway genes (CTNNB1, AXIN2, LRP5 and LRP6) for association with diabetic nephropathy using a case-control design." (PMID 21876774, 2011). "Our results suggest that analysed common variants in CTNNB1, AXIN2, LRP5 and LRP6 are not strongly associated with diabetic nephropathy in type 1 diabetes among white individuals." (PMID 21876774, 2011).
endometritis (1 paper, 2020). An acute or chronic, usually bacterial infectious process affecting the endometrium. "The results revealed the dysregulation of the six crucial biomarkers involved in endometritis: SLC7A5, COL1A1, AXIN2 (upregulated); CFD, MGP, CCDC3 (downregulated)." (PMID 32545766, 2020). "This study confirmed differences in the expression profiles of six biomarkers in LPS-induced bovine endometritis: SLC7A5, COL1A1, AXIN2 (upregulated) and CFD, MGP, CCDC3 (downregulated)." (PMID 32545766, 2020).
fibrosis (1 paper, 2015). the formation of excess fibrous connective tissue in an organ or tissue in a reparative or reactive process. "mRNA levels of axin-2 were significantly increased in human fibrotic diseases and in murine experimental fibrosis." (PMID 25797248, 2015).
gastric adenocarcinoma (1 paper, 2018). "In addition, C59 treatment suppresses transcription of Axin2 and TCF1, both of which are the target genes of β-catenin in gastric adenocarcinoma cells." (PMID 30089773, 2018).